BRAF (B-Raf proto-oncogene, serine/threonine kinase)
Diseases named in the same sentence as BRAF in open-access papers (continued):
Sharing a sentence is not in itself a finding about the gene and the disease.
melanoma (continued). "The combined therapy was initiated in patients with aggressive advanced melanoma (3 or more metastatic sites, ECOG > 1, or high LDH level), half of them harboring brain metastasis, all previously treated with TKI (for BRAF-mutated melanoma patients) or ICI." (PMID 32585901, 2020). "PA precipitation has been reported to improve sensitivity of BRAF-V600E detection in melanoma patient plasma and to improve detection of low-frequency mutations in prostate cancer patients by ddPCR analysis." (PMID 33260345, 2020). "For the present meta-analysis, correlations to patients with BRAF, NRAS, and KIT mutations, clinical-pathological characteristics and risk factors correlated to the development of melanoma were grouped together." (PMID 31274706, 2020). "In patients with melanoma who received adoptive transfer of activated autologous TILs, ctDNA analysis for BRAF V600E (n = 48, 388 serum samples) demonstrated a strong correlation between an early peak of circulating V600E mutation and objective response." (PMID 32010431, 2020). "Our findings are consistent with recent reports evaluating the clinical activity of BRAF‐targeted therapies or immune checkpoint inhibitors in patients with melanoma CNS metastases." (PMID 32667719, 2020). "Mutations in genes encoding BRAF and NRAS proteins are the most common mutations found in melanoma, where approximately 50% of melanomas harbor a BRAF mutation and about 20% carry an NRAS mutation." (PMID 32726988, 2020). "Four melanoma cell lines (MM050, MM074, MM164 and SKMEL-28), all with BRAF V600E mutations, were made resistant to the BRAF V600E inhibitor vemurafenib after chronic exposure for 12 weeks to gradually increasing concentrations of vemurafenib (0.1–2 μM)." (PMID 32098410, 2020). "In contrast, drug-resistant melanoma cells subjected to Gal-1 knock-down maintained sensitivity to the BRAF inhibitor PLX-4720 and their viability decreased remarkably." (PMID 32784465, 2020). "A total of 322 patients affected by previously untreated BRAF V600 E/K stage III or IV melanoma were enrolled." (PMID 32850962, 2020). "In melanoma, ERK activation is most commonly due to the mutations of BRAF, followed by RAS, NF1, and other genes." (PMID 32083130, 2020). "Vemurafenib is a specific and potent BRAF inhibitor that significantly prolongs progression-free survival in patients with BRAF mutant melanoma." (PMID 32382617, 2020). "The main goal of the present study was to find new treatment options to restore PMCA4b expression and/or function with possible impact on the metastatic activity of BRAF mutant melanoma cells." (PMID 32414111, 2020). "YAP augments PD-L1 expression in EGFR inhibitor-resistant lung cancer, pancreatic cancer, mesothelioma and BRAF inhibitor-resistant melanoma." (PMID 32992658, 2020). "It is this monomer that various BRAF inhibitors used for melanoma therapy, like vemurafenib, dabrafenib and encorafenib, bind." (PMID 32605090, 2020). "This is consistent with previous finding that BRAF-V600E can downregulate BIM expression in melanoma." (PMID 32764384, 2020). "To investigate the mechanisms and pathways enabling resistance to BRAF inhibitors in melanomas, we integrate expression, ATAC-seq, and CRISPR screen data." (PMID 32413516, 2020). "Upregulation of Axl leads to drug resistance of BRAF directed therapies in the context of melanoma and also reduces response to PD-1 blockade." (PMID 32092958, 2020). "The miR-506-514 cluster is overexpressed in melanoma and involved in melanocyte transformation, melanoma growth, and sensitivity to BRAF inhibitors." (PMID 33330090, 2020). "BRAF mutations are reported in about 7% of solid tumors, with a high prevalence in PTC, melanoma, colorectal cancer, and lung cancer." (PMID 33260892, 2020).
melanoma (continued). "Inhibitors of oncogenic BRAF, which occurs in ∼50% of melanoma patients, have led to unprecedented clinical responses in patients with BRAF mutant metastatic melanoma." (PMID 32241802, 2020). "Target therapy with combination of a BRAF and a MEK inhibitor has dramatically improved the clinical perspective of BRAF-mutated melanoma patients." (PMID 32178301, 2020). "Another important example is the combination of BRAF and MEK inhibition with dabrafenib and trametinib or vemurafenib and cobimetinib for the treatment of melanoma harboring a BRAF V600E mutation." (PMID 33114048, 2020). "To exemplify the framework, we use pairwise combination measurements of 104 drug compounds in 60 cancer cell lines from the NCI-ALMANAC resource, and subsequently experimentally validate the most interesting predictions in BRAF-V600E melanoma cell line." (PMID 33370253, 2020). "The first drug belonging to this class that has been approved for melanoma is vemurafenib, a selective inhibitor of V600-mutant BRAF." (PMID 33092131, 2020). "The reason it is important to clarify how BRAF-transformed nevus melanocytes stop growing is that it shapes how we think about the origins of melanoma." (PMID 33047672, 2020). "Adjuvant treatment of operated melanoma has deeply changed in the last few years with the introduction of immune-checkpoint inhibitors and BRAF/MEK inhibitors." (PMID 33312171, 2020). "At the present time, three selective BRAF kinase inhibitors have been approved for use in the treatment of BRAF-mutant melanoma, including vemurafenib, dabrafenib and encorafenib." (PMID 32645969, 2020). "A major component of melanoma development is the constitutive activation of the MAPK pathway, predominantly resulting from BRAF or NRAS mutations, which contributes to increased cell proliferation and survival." (PMID 32637352, 2020). "The distribution of melanoma subtypes, BRAF status, and baseline clinical characteristics of our study patients comprise a representative cohort of MBM patients." (PMID 32249551, 2020). "Few studies have shown that JQ1 can act synergistically with vemurafenib in BRAF mutant melanoma models." (PMID 32231230, 2020). "We investigate a possible role for DUSP4 and ETV4 in mediating this response by assessing the effect of their depletion on the sensitivity of BRAF wild-type melanoma cells to MEK inhibition." (PMID 31839677, 2020). "Actually, preliminary data suggested that the conditioned medium of PLX4720-resistant melanoma cells contained bona fide soluble factors capable of promoting resistance to BRAF inhibitors." (PMID 32784465, 2020). "The MAPK pathway, which is constitutively activated by BRAF and NRAS mutations in melanoma, is positively associated with iNOS expression." (PMID 32850409, 2020). "Adaptive tumour responses to BRAF‐targeted drugs are favoured by melanoma heterogeneity and lead to treatment failure." (PMID 31758648, 2020). "This complicated multifaceted role of MITF in melanoma is also reflected in its role in the mechanisms of resistance to BRAF inhibition." (PMID 32605090, 2020). "Several studies have demonstrated that inhibition of the PI3K/AKT pathway sensitizes melanoma cells to BRAF/MEK/ERK pathway inhibitors." (PMID 32340351, 2020). "Therapeutic success of targeted therapy with BRAF inhibitors (BRAFi) for melanoma is limited by resistance development." (PMID 31702822, 2020). "Here, we utilised a new BETi, PLX51107, in combination with BRAFi/MEKi in BRAF-mutant melanoma models to broadly suppress adaptive upregulation of RTKs in response to targeted therapy." (PMID 31932756, 2020). "In this study, melanoma mutant gene BRAF V600E was edited by the CRISPR gene-editing tool, resulting in an obvious killing effect on tumor cells." (PMID 33330635, 2020). "DTIC was one of the standard therapies for the treatment of advanced melanoma before ICIs or BRAF inhibitors became available for clinical use." (PMID 32948031, 2020).
melanoma (continued). "This phenomenon has also been observed following PD0325901 treatment, with a concomitant decrease in total MEK, in HCT116 colorectal cancer cells as well as in BRAF V600E mutant melanoma cells." (PMID 33283192, 2020). "Two phase III studies reported objective response rates of ~50% and a median progression-free survival of ~5.3 months for vemurafenib and dabrafenib in patients with BRAF V600-positive melanoma." (PMID 32714388, 2020). "In our previous study we found that Ole affects both the proliferation and the viability of A375 BRAF melanoma cells and potentiates their therapy response through pAKT/mTOR pathway." (PMID 32013090, 2020). "So far, apart from the BRAF-MEK combination in melanoma, few combinations of two RTKIs have been used clinically." (PMID 32244867, 2020). "RAL was described as an inducer of proliferation in melanoma cell lines, even in the presence of NRAS and/or BRAF oncogenic mutations." (PMID 33072757, 2020). "At preclinical level, it inhibits BRAFV600E kinase activity determining cell growth inhibition in vitro and tumor regression in vivo in mouse models of BRAF-mutant melanoma." (PMID 33036192, 2020). "A recent clinical trial, conducted on 577 BRAF-mutant melanoma patients, showed that encorafenib alone or in combination with binimetinib (MEK inhibitor) brings benefits, in terms of survival and tolerability, as compared to treatment with vemurafenib alone." (PMID 33036192, 2020). "NCT03554083 is studying the effect of combined treatment with cobimetinib (MEK inhibitor) and atezolizumab (PD-L1-Ab), and with vemurafenib (BRAF inhibitor), cobimetinib, and atezolizumab for the treatment of patients with high-risk stage III melanoma." (PMID 32260561, 2020). "The assays were validated using three melanoma cell lines with resistance to BRAF inhibition and known to express alternative BRAF splicing variants." (PMID 33216826, 2020). "When different BH3-mimetics were tested on melanoma cell lines (including wild-type and mutant BRAF and NRAS lines), all cell lines were found to be resistant to the individual drugs." (PMID 33308268, 2020). "We recently demonstrated that the melanoma cell-autonomous survival in response to the BRAF inhibitor vemurafenib is mediated by S1P1 and S1P3." (PMID 32858889, 2020). "With the recent emergence of next-generation-sequencing (NGS) analyses, concomitant somatic genomic alterations have been identified in samples of BRAF mutant melanomas, such as CDKN2A, PTEN, RAC1, and TERT promoter." (PMID 32784823, 2020). "Patients with advanced melanoma are often treated with v-raf murine sarcoma viral oncogene homolog B1 (BRAF) inhibitors." (PMID 33003483, 2020). "Contrarily, SIRT2 loss has also been shown to confer resistance to BRAF and MEK inhibitors in BRAF mutant melanoma." (PMID 33178616, 2020). "In GPX4 knockout melanoma cells it was demonstrated that increased ferroptosis sensitivity can be seen when combining ferroptosis-inducing drugs with BRAF inhibition." (PMID 32509589, 2020). "Using, a combination of transcriptomic, epigenomic and proteomic analyses we demonstrated that haploinsufficiency of SIRT6 in BRAF-mutant melanoma cells decreases sensitivity to MAPKi independently of the ERK signaling pathway." (PMID 32042336, 2020). "Transdermal (topical) delivery of siRNA targeting BRAF to mice melanoma model using carbon nanotube functionalized with polyethylenimine (PEI) attenuated tumor growth over 25-day period." (PMID 32059541, 2020). "cfDNA was analyzed for BRAF p.V600E, NRAS p.Q61K/p.Q61R, and TERT C228T mutations, as these are frequently found in melanoma patients." (PMID 32486146, 2020). "While both aPD‐1 and BRAF/MEKi are approved for BRAF‐mutant advanced melanoma, limited evidence exists comparing these therapies, particularly to understand the optimal treatment sequence." (PMID 32871054, 2020).
melanoma (continued). "As recently reviewed, nicotinamide phosphoribosyltransferase (NAMPT) plays a critical role in NAD+ synthesis and energy control and its role in melanoma, mediated by BRAF and Sirtuins, is being recognized with increasing evidence." (PMID 33028392, 2020). "This review examines all of the potential ways that melanoma cells develop resistance to BRAF inhibitors." (PMID 33003483, 2020). "BRAF inhibition has been shown to increase melanoma cell immunogenicity, but these effects are transient and rapidly exhaustible." (PMID 32330348, 2020). "We report a case of a 38-year-old woman with stage III operated melanoma treated with adjuvant BRAF plus MEK inhibitors, who developed sarcoidosis-like syndrome with systemic involvement, resolved after discontinuation of treatment." (PMID 33312171, 2020). "We found that ETV5 deletion restored sensitivity to BRAF inhibition by PLX4720 in melanoma cells and ETV5 was the top hit of the genes that were more essential in M238R1 cells under the BRAFi treatment." (PMID 32413516, 2020). "In summary, targeted therapy with BRAF plus MEK inhibitors has radically changed the therapeutic landscape of melanoma, both in the advanced and the adjuvant setting." (PMID 32760738, 2020). "Taken together, these data suggest that Ponatinib is an effective BRAF inhibitor that inhibits melanoma cells dependent on BRAFV600E monomers and dimers as well as mutant RAS-activated BRAFWT dimers with less potency." (PMID 32873792, 2020). "Treatment of advanced BRAF V600E mutant melanoma using a BRAF inhibitor or its combination with a MEK inhibitor typically elicits only partial response." (PMID 35582613, 2020). "Very promising results were obtained in a study in which spartalizumab (anti-PD-1 antibody), coupled with dabrafenib and trametinib, was used to treat patients with advanced BRAF mutant melanoma." (PMID 33171792, 2020). "We further delineated the mutation patterns of 4 molecular subgroups (BRAF, RAS, NF1, and Triple-WT) of melanoma in our cohort." (PMID 32083130, 2020). "This study provides evidence of a clinical benefit of first‐line (1L) aPD‐1 compared to BRAF/MEKi after 6 months among patients with BRAF‐mutant advanced melanoma who received care in a large network of US community oncology clinics." (PMID 32871054, 2020). "Previous studies have demonstrated that activation of NF-κB pathway confers a protective activity on melanoma cells subjected to BRAF inhibition." (PMID 32565808, 2020). "This was evidenced for KRAS wild-type squamous cell carcinomas that acquired resistance to cetuximab and proofed for BRAF (V600E)-mutant melanoma cells that became resistant to vemurafenib." (PMID 31948066, 2020). "The high Axl, low MITF drug resistance phenotype is found frequently among BRAF mutant melanoma cell lines." (PMID 32092958, 2020). "In melanoma, mutations of genes of the RAS‐family have been shown to be a major mechanism of resistance to BRAF inhibition." (PMID 35847743, 2020). "For example, one of our patients with widespread metastases of melanoma showed both a GNA11 Q209L and a BRAF V600K mutation." (PMID 32718045, 2020). "The multiplicity of potential targets raises the possibility of using genomic and proteomic data to personalize combination therapy towards the specific pathway that is activated during BRAF inhibitor resistance in individual patients with melanoma." (PMID 33003483, 2020). "Acquired resistance of melanoma patients to inhibitors of BRAF (BRAFi) and MEK (MEKi), which block the mitogen-activated protein kinase (MAPK) pathway, limits their prolonged use." (PMID 32604720, 2020). "Along with BRAF mutations, NRAS mutations are among mutations found in melanocytic and dysplastic nevi and melanomas, with high mutational load as a notable discriminant favoring the latter in diagnosis." (PMID 32429485, 2020).
melanoma (continued). "Targeted inhibition of the mitogen-activated protein kinase (MAPK) pathway with selective BRAF and MEK inhibitors presents a new strategy to treat metastatic melanomas harboring BRAF mutations." (PMID 33184267, 2020). "Concomitant administration of PLX4720 and SBI-756 in melanoma xenograft models mitigated the formation of BRAF-inhibitor-resistant tumors." (PMID 32517051, 2020). "The combined blockade of Galectin-1 and NRP1 in drug-resistant melanoma cells restored BRAF-addiction and sensitivity to therapy." (PMID 32784465, 2020). "Advancements in our understanding of dysregulated signaling pathways in melanoma have resulted in the development of drugs targeting pathway alterations, such as BRAF and MEK1/2 inhibitors." (PMID 32637352, 2020). "In other studies, SVM effectively discriminated melanoma on the basis of dermoscopic images, ultrasonic and spectrophotometric images, BRAF status, or dermo-fluorescence spectra, with a reported accuracy up to 90%." (PMID 33302400, 2020). "Most BRAF-resistant melanomas also involve additional mutations in the MAPK pathways, e.g., MEK1 mutations and BRAF amplification." (PMID 32213878, 2020). "Simultaneous downregulation of both RAF and MET reverted resistance in vitro, and it has been proposed as a possible therapeutic approach for the treatment of BRAF-mutant melanomas." (PMID 33036192, 2020). "The BRAF inhibitors which are currently used in treating melanoma, rewire metabolism and enhance ROS production." (PMID 32477956, 2020). "Overall, over 90% of BRAFV600-mutated melanomas harbor a BRAFV600E mutation, 6% a BRAFV600R mutation, and 4% a BRAFV600E2, BRAFV600D, or a BRAFV600K mutation, and therefore mutated BRAF kinase became an attractive therapeutic target." (PMID 33014862, 2020). "The same applies for melanoma cells with BRAF and NRAS wild-type proteins as we demonstrated in a previous study." (PMID 32098410, 2020). "To date, oncogenic BRAF has been targeted with varying success scale in humans in melanoma, non-small cell lung cancer, colorectal carcinoma, and thyroid carcinoma, as well as gliomas and glioneuronal tumors." (PMID 33042847, 2020). "The duration of responses to targeted inhibitors in BRAF-mutant melanoma is limited by rapid adaptations that select for drug-tolerant cell subpopulations." (PMID 31932756, 2020). "Oncogenic RAS signaling increases PD-L1 expression though c-Jun binding, such as in BRAF inhibitor-resistant melanoma, and via stabilization of PD-L1 mRNA, such as in lung and colorectal tumors." (PMID 32992658, 2020). "The systematic evaluation of over 500 melanoma genomes in the last decade has identified a series of frequently and significantly altered oncogenes and tumor suppressor genes, including BRAF, NRAS, RAC1, NF1, CDKN2A, PTEN, and ARID2." (PMID 33076392, 2020). "Ipilimumab, an anti-CTLA-4 mAb, shows a better effect on survival improvement in melanoma patients carrying the BRAF wild type compared to radiotherapy and chemotherapy." (PMID 32013263, 2020). "Determining the expression levels of MITF and other factors that promote metastasis and phenotype switching, allows to distinguish between melanoma cells that are sensitive or resistant to BRAF inhibitor." (PMID 33167306, 2020). "To date, four MEK inhibitors–trametinib, cobimetinib, binimetinib, and selumetinib, as single agent or in combination with BRAF inhibitors–have been approved for melanoma/NSCLC/neurofibromas." (PMID 33109256, 2020). "Extending it to clinical settings, a cohort of primary and metastatic melanoma human biopsies bearing BRAFV600E/K gene mutation showed a higher immunoexpression of Cav3.1 compared with a BRAF wild-type melanoma cohort." (PMID 32046241, 2020). "Another arginine transporter, CAT-2 (SLC7A2), is highly expressed in BRAF (v-raf murine sarcoma viral oncogene homolog B1) inhibitor-resistant melanoma, displaying metabolic reprogramming from glucose to arginine dependence." (PMID 33511116, 2020).